SPRY2 (sprouty RTK signaling antagonist 2)
Diseases named in the same sentence as SPRY2 in open-access papers (continued):
Sharing a sentence is not in itself a finding about the gene and the disease.
pancreatic cancer (6 papers, 2013 to 2024). "It promotes EGF-induced pancreatic cancer cell proliferation by targeting Spry2, and the mechanistic revealed that miR-21 targeted MAPK/ERK and PI3K/AKT signaling pathways to modulate cell proliferation." (PMID 36688087, 2023). "In summary, our results suggested that miR-21 directly recognized the 3′-UTR of Spry2 mRNA and regulated Spry2 expression by degrading Spry2 mRNA in pancreatic cancer cells." (PMID 30464258, 2018). "Then, flow cytometric analysis was performed to examine the effect of Spry2 on pancreatic cancer cell proliferation through alteration of altering cell cycle progression and cell apoptosis." (PMID 30464258, 2018). "Consistent with the function of Spry2 detected in our study, Spry2 protein expression was low in pancreatic cancer tissues, and downregulated Spry2 expression was associated with pathological grade, T stage, N stage and AJCC stage (P < 0.05 for all)." (PMID 30464258, 2018). "Inhibition of miR-27a was, moreover, found to suppress the growth, colony formation, and migration of pancreatic cancer cells by targeting Spry2." (PMID 25915942, 2015). "Here, we showed that both miR-21 and Spry2 could affect MAPK/ERK and PI3K/AKT signal pathway, which further explains the role of miR-21 and Spry2 in pancreatic cancer cell proliferation." (PMID 30464258, 2018). "Then, we conducted a series of experiments to assess whether Spry2 alone was sufficient to modulate EGF signaling in pancreatic cancer cells." (PMID 30464258, 2018). "Furthermore, we show that miR-21 and Spry2 are correlated with pancreatic cancer clinical pathological features." (PMID 30464258, 2018). "We further confirmed that Spry2 was poorly expressed in pancreatic cancer tissues." (PMID 30464258, 2018). "Moreover, we further verified that Spry2, as a direct target of miR-21, could mediated the effects of miR-21 on pancreatic cancer cell proliferation by inhibiting MAPK/ERK and PI3K/AKT signal pathway." (PMID 30464258, 2018). "Inhibition of miRNA-27a suppressed the growth, colony formation, and migration of pancreatic cancer cells, and further data indicated that miRNA-27a played an oncogenic role and modulated the malignant, biological behavior of pancreatic cancer cells by targeting SPRY2." (PMID 24587996, 2014). "Further, it inhibits SPRY2 mRNA, a crucial inhibitor of the Ras/MAPK signaling pathway, and promotes cell proliferation and migration in pancreatic cancer cell lines such as PANC-1 and MIA PaCa-2." (PMID 23472065, 2013). "More importantly, ISH and IHC scores revealed that there was a negative correlation between miR-21 and Spry2 in pancreatic cancer tissues." (PMID 30464258, 2018).
malignant glioma (5 papers, 2015 to 2025). A grade III or grade IV glioma arising from the central nervous system. "In contrast, SPRY2 is overexpressed in malignant gliomas (GBM) suggesting a potential oncogenic function in brain cancer." (PMID 34685612, 2021). "In summary, apart from malignant gliomas, CRC is the second example where SPRY2 expression is increased and is responsible for augmenting cancer phenotype." (PMID 34685612, 2021). "Other studies found no increase in SPRY2 mRNA but reduced SPRY2 protein levels in higher malignant gliomas." (PMID 41516252, 2025).
cleft palate (4 papers, 2009 to 2022). Cleft palate is a fissure type embryopathy that affects the soft and hard palate to varying degrees. "The piebald deletion led to a high incidence of cleft palate while the targeted deletion of Spry2 only displayed the cleft palate phenotype in approximately 20% of animals." (PMID 23316168, 2012). "Mice carrying a large deletion of chromosome 14 (Pub36-/-), a region that contains the Spry2 gene exhibit cleft palate, excessive cell proliferation and up regulation of FGF target genes including Msx1, Etv5 and Barx1." (PMID 20459789, 2010). "Knockout of Spry2, which is a negative regulator of the ERK/MAPK signal transduction pathway involved in palatal shelf elevation, resulted in cleft palate via FGF signaling, indicating that over-activation of ERK/MAPK can cause cleft palate." (PMID 35997397, 2022). "The link between ETV5, SPRY2 and members of the FGF family offers an exciting opportunity to further explore these interacting developmental pathways in the pathogenesis of cleft palate." (PMID 19401770, 2009).
diabetes (4 papers, 2018 to 2025). "Novel VaD loci were associated with hypertension, diabetes, and neuron maintenance (SPRY2, FOXA2, AJAP1, and PSMA3)." (PMID 39046104, 2024). "SPRY2 was significantly associated with body fat percentage and type 2 diabetes mellitus in large genetic studies." (PMID 33414381, 2021). "Similarly, the two strongest weighted loci in Cluster 2 are ARAP1, a locus at which diabetes risk is thought to be mediated by modulation of STARD10 expression in pancreatic beta cells, and SPRY2, a locus at which the closest gene, SPRY2, regulates insulin transcription." (PMID 30240442, 2018).
gastric cancer (4 papers, 2017 to 2025). A primary or metastatic malignant neoplasm involving the stomach. "Experiments in vitro and in vivo were performed to further explore FGFR2 and SPRY2 significance on gastric cancer progression." (PMID 28002800, 2017). "Cells with FLAG-SPRY2 transfection had significantly higher SPRY expression but lower ERK phosphorylation, which confirmed that SPRY2 inhibited FGF-induced ERK phosphorylation in gastric cancer cells." (PMID 28002800, 2017). "We hope our findings could expand the understanding of SPRY2 in gastric adenocarcinoma, help find a new chemotherapy and improve the survival rates for patients with gastric cancer." (PMID 28002800, 2017). "In summary, above observations suggested that FGFR2 could facilitate cell proliferation and invasion in gastric cancer, and SPRY2 functioned as an antagonism in this process." (PMID 28002800, 2017). "We proved that SPRY2 is an unfavourable biomarker for gastric cancer prognosis in our study." (PMID 28002800, 2017). "Additionally, we further explored the role of SPRY2 on progression of gastric cancer with experiments in vitro and in vivo." (PMID 28002800, 2017). "SPRY2 can antagonize FGFR2-induced proliferation and invasion via suppressing ERK phosphorylation in gastric cancer cells, indicating SPRY2 as a potential therapeutic target for gastric adenocarcinoma treatment." (PMID 28002800, 2017). "We also proved that SPRY2 could inhibit FGFR2-induced ERK phosphorylation and suppress FGFR2-elicited gastric cancer cell proliferation and invasion." (PMID 28002800, 2017).
B-cell lymphoma (3 papers, 2014 to 2024). "In conclusion, they implicated Spry2 in regulation of TCL1-augmented ERK signaling and B-cell proliferation and suggested Spry2 epigenetic silencing as an aberration contributing to B-cell lymphoma progression." (PMID 24744103, 2014).
breast tumor (3 papers, 2011 to 2023). "In conclusion, our study showed that dysregulated SPRY2 in TME could promote breast tumor development." (PMID 37507768, 2023). "Since higher levels of Spry2 were associated with increased therapeutic efficacy in the HER2+ SKBr3 breast cell line, we quantified expression of Spry2 in 122 primary breast tumours from patients who had been treated with trastuzumab using the AQUA fluorescence image analysis system." (PMID 21909357, 2011). "By contrast, Spry1 was low in MCF-7 cells, higher in MDA-MB-231 and MDA-MB-157 cells, and Spry2 protein was undetectable in all three MCF-7, MDA-MB-231 and MDA-MB157 breast tumor cell lines." (PMID 26976794, 2016).
depression (3 papers, 2015 to 2021). "GWAS depression genes were among depression portrait genes and common genes of interest included SPRY2 and PSEN2." (PMID 33589676, 2021). "We show that ECS—which models key aspects of ECT, a treatment with particularly high efficacy in people with depressive disorders —produces a downregulation of the growth factor inhibitor SPRY2 in the dorsal HIP." (PMID 25822989, 2015). "Further genetic studies may reveal the role of SPRY2 in both depression and obesity, particularly in females." (PMID 33414381, 2021).
lymphoma (3 papers, 2014 to 2023). A malignant (clonal) proliferation of B- lymphocytes or T- lymphocytes which involves the lymph nodes, bone marrow and/or extranodal sites. "Five out of seven diffuse large B-cell lymphomas and the only Burkitt’s lymphoma sample studied contained DNA methylation of the Spry2 promoter which was associated with repressed Spry2 expression in 4 out of 6 lymphoma samples." (PMID 24744103, 2014).
prostate tumour (3 papers, 2014 to 2020). "We propose targeting cholesterol bioavailability using statins or tumoral cholesterol uptake using ITX5061, a clinically safe SRB1 antagonist, as two strategies to sensitise prostate tumours with SPRY2 deficiency or HER2 activation to the standard‐of‐care androgen deprivation therapy." (PMID 29540470, 2018). "We next investigated SPRY2 status in hormone‐naïve (HN) and CRPC matched tissue microarray comprising of prostate tumour biopsy pairs at diagnosis and after recurrence from the same individuals." (PMID 29540470, 2018).
renal cell carcinoma (3 papers, 2015 to 2022). "Recently, it has been shown that inhibiting Spry2 expression in renal cell carcinoma promotes proliferation and invasion highlighting thus a potential role for Spry2 during tumorigenesis." (PMID 25783674, 2015).
schizophrenia (3 papers, 2008 to 2024). A major psychotic disorder characterized by abnormalities in the perception or expression of reality. "In 2008, Pillai A examined the possibility that the aberrant expression of the GF signaling regulator SPRY2 was linked to alterations in BDNF mRNA levels in schizophrenia." (PMID 39456824, 2024). "Considering neurotrophin involvement in the neuropathogenesis of schizophrenia, the possible role of Spry2, a prototypical member of the sprouty family, was investigated in schizophrenia." (PMID 18335055, 2008). "The present study for the first time shows that the expression of Spry2, a key regulator of growth factor signaling, is altered in schizophrenia and bipolar disorder compared with normal controls." (PMID 18335055, 2008). "Further exploration of Spry2-related signal transduction pathways will be helpful to design novel treatment strategies for schizophrenia and bipolar disorder." (PMID 18335055, 2008). "The data from the present study suggest that Spry2 gene expression is significantly decreased in patients with either schizophrenia or bipolar disorder." (PMID 18335055, 2008). "A significant reduction in mean Spry2 mRNA levels was observed in the schizophrenia (33%; p = 0.0098) and bipolar groups (46%; p = 0.003) compared to the control group." (PMID 18335055, 2008). "Therefore, additional studies are needed to correlate Spry2 expression and ERK signaling in schizophrenia, which will help to identify the downstream signaling pathways regulated by Spry2 in schizophrenia." (PMID 18335055, 2008). "The results of this study, which show a correlation between alterations in BDNF and decreased expression of SPRY2, raise the idea that the latter is the result of treatment-related factors rather than important elements in the pathophysiology of bipolar illness or schizophrenia." (PMID 39456824, 2024). "In both bipolar disorder and schizophrenia, there is a considerable decrease in the expression of BDNF and SPRY2, according to quantitative real-time polymerase chain reaction analysis of RNA in 100 individuals." (PMID 39456824, 2024). "Second, a significant positive correlation was observed between Spry2 and BDNF in schizophrenia, bipolar and normal subjects." (PMID 18335055, 2008). "The key findings from the present study are: First, gene expression of Spry2 and BDNF, a known inducer of Spry2, are down-regulated in the DLPFC of schizophrenia and bipolar subjects." (PMID 18335055, 2008). "Significant high correlation between Spry2 and BDNF mRNA expression levels was found in schizophrenia group (p = 0.01), bipolar group (p = 0.02) and control group (p = 0.016)." (PMID 18335055, 2008). "The changes in Spry2 mRNA expression were significantly correlated with BDNF mRNA expression in schizophrenia, bipolar and normal subjects suggesting the importance of BDNF in the regulation of Spry2 expression." (PMID 18335055, 2008). "The expression of BDNF and Spry2 was examined by quantitative real-time PCR (qRT-PCR) in the Stanley Array Collection, derived from dorsolateral prefrontal cortex (DLPFC) of individuals with schizophrenia, bipolar disorder, or psychiatrically normal controls." (PMID 18335055, 2008). "Taken together, our data from postmortem as well as animal studies indicate that the altered expression of Spry2 may be secondary to antipsychotic treatment rather than to factors that are significant in the disease process of either schizophrenia and/or bipolar disorder." (PMID 18335055, 2008).
adrenal cortex adenocarcinoma (2 papers, 2010 to 2024). "Mediated by small inhibitory rna, endogenous human SPRY2 (hSPRY2) silencing can eliminate the antiapoptotic effect of serum on adrenal cortical adenocarcinoma (SW13) cells." (PMID 39130630, 2024). "Edwin and coworkers notably demonstrated that silencing of SPRY2 abolishes the anti-apoptotic action of serum in adrenal cortex adenocarcinoma cells." (PMID 20813052, 2010).
allergic asthma (2 papers, 2020 to 2021). A asthma with a basis in a pathological type I hypersensitivity reaction. "Next, we studied the role of Spry2 in airway type 2 inflammation in a mouse model of allergic asthma." (PMID 33684096, 2021). "As M2 cells are the major effector macrophages in allergic asthma, it is conceivable that Spry2 deletion increased the abundance of this population." (PMID 32731503, 2020). "Interestingly, in a model of allergic asthma, Spry2 deletion significantly increased the number of macrophages." (PMID 32731503, 2020).
bipolar disorder (2 papers, 2008 to 2021). A disorder of the brain that causes unusual shifts in mood, energy, activity levels and the ability to carry out day-to-day tasks. "Spry2 expression was significantly low (p = 0.037) in antipsychotic-naive patients with bipolar disorder (n = 12) compared to control subjects." (PMID 18335055, 2008).
Bladder cancer (2 papers, 2017 to 2021). "An association of methylation of TBX2 and SPRY2 with disease progression has also been demonstrated in bladder cancer and B-cell diffuse lymphoma, respectively, but so far, no studies have been reported in CLL." (PMID 28572861, 2017).
Chronic colitis (2 papers, 2021 to 2023). A chronic inflammatory disease of the large intestine (colon, cecum and rectum). "Recent reports have cited increased expression of SPRY2 involved in chronic colitis and inflammatory bowel disease." (PMID 36384366, 2023). "Consistent with this, in the IL-10−/− chronic colitis model, Spry2 is elevated in colonic homogenates from adult animals with active inflammation versus young (pre-colitic) littermates, and these mice express reduced levels of tuft (Trpm5) and goblet cell (Muc2) markers in the distal colon." (PMID 33547321, 2021).
colitis (2 papers, 2021). Inflammation of the colon. "In acute experimental colitis, we observed loss of Spry2 rapidly during the injury phase, which correlated with increased IL-33 levels." (PMID 33547321, 2021). "More importantly, they revealed the underlying mechanism using a SPRY2 KO mice model and found that in response to acute colitis, deletion/suppression of SPRY2 played a protective role in maintaining the integrity of the colon epithelium against inflammation." (PMID 34685612, 2021). "While it might seem surprising that SPRY2 levels are elevated in IBD when they are suppressed in DSS colitis, our data with multiple models suggest that inhibition of Sprouty2 is lost in chronic inflammation." (PMID 33547321, 2021). "As IL-33 may be protective in human IBD, expanded studies correlating Sprouty2, IL-33, and colitis outcomes will be important to pursue to determine whether SPRY2 acts as a biomarker for disease severity." (PMID 33547321, 2021). "To consider whether this mechanism might be defective in IBD, we measured SPRY2 expression in colon endoscopic mucosal biopsies from pediatric IBD patients with active colonic inflammation and non-IBD controls." (PMID 33547321, 2021).
colorectal tumors (2 papers, 2012 to 2021). "Taken together, this is the first study to our knowledge to demonstrate that putative CTCF binding regulatory regions #1 and #4 are mostly hypomethylated in colorectal tumors, which correlates with overall increased SPRY2 protein expression." (PMID 34685612, 2021). "A total of 7/10 colorectal tumors displayed hypomethylation in either SPRY2 regions #1 and/or #4." (PMID 34685612, 2021).
Crohn disease (2 papers, 2021). A gastrointestinal disorder characterized by chronic inflammation involving all layers of the intestinal wall, noncaseating granulomas affecting the intestinal wall and regional lymph nodes, and transmural fibrosis. "We found elevated SPRY2 expression in both ulcerative colitis and Crohn’s disease patients." (PMID 33547321, 2021). "Furthermore, another recent study found that SPRY2 was increased in colon epithelial cells in patients with ulcerative colitis and Crohn’s disease." (PMID 34685612, 2021).
diabetes type 2 (2 papers, 2019 to 2021). "Previous GWAS studies have associated the SPRY2 gene with adiposity and metabolism impairment, and with diabetes type 2 in Asian cohorts." (PMID 31791255, 2019). "This suggests that decreased expression of SPRY2 in human hepatocytes contributes to the pathogenesis of obesity and type 2 diabetes." (PMID 33414381, 2021).
hyperglycaemia (2 papers, 2019). "The importance of the association is possibly highlighted by a study that found that mice displayed hyperglycemia when the SPRY2 gene is knocked down, indicating that it is possible that the rate/extent of glucose formation is influenced by the SPRY2 gene." (PMID 31791255, 2019). "In a recent study utilising whole-genome RNAi, SPRY2 was identified as a novel regulator of insulin transcription, and deletion of SPRY2 in adult mouse β-cells led to mild hyperglycaemia and hypoinsulinaemia." (PMID 31664995, 2019).
leiomyosarcoma (2 papers, 2014 to 2018). An uncommon, aggressive malignant smooth muscle neoplasm, usually occurring in post-menopausal women. "For example, overexpression of SPRY2 negatively regulated HGF-mediated ERK and AKT signaling in human leiomyosarcoma, whereas SPRY2 overexpression increased MET activation resulting in enhanced cell migration and invasion in colonic adenocarcinomas." (PMID 29445192, 2018). "SPRY2 modulates MET signaling in cancer types such as leiomyosarcomas, hepatocarcinomas, and colonic adenocarcinomas." (PMID 29445192, 2018).
liver fibrosis (2 papers, 2014 to 2023). "MiR-21 modulates ERK1 signaling and EMT in liver fibrosis by regulating SPRY2 and HNF4α expression." (PMID 25303175, 2014).
Obesity (2 papers, 2019 to 2021). Accumulation of substantial excess body fat. "The lead variant (rs534870), 54 kb downstream of SPRY2, exhibited a modest association with BMI, body weight and risk of obesity; importantly, its major allele was associated with a 0.14% decrease in BF% in individuals of European descent." (PMID 31664995, 2019). "Further studies will be required to explore the potential link between SPRY2 and these genes in the context of obesity and T2DM, and in particular, the potential role of SPRY2 in the pathogenesis of liver diseases, such as NAFLD." (PMID 31664995, 2019).